UPF3B (UPF3B regulator of nonsense mediated mRNA decay)
Description:
Involved in nonsense-mediated decay (NMD) of mRNAs containing premature stop codons by associating with the nuclear exon junction complex (EJC) and serving as link between the EJC core and NMD machinery. Recruits UPF2 at the cytoplasmic side of the nuclear envelope and the subsequent formation of an UPF1-UPF2-UPF3 surveillance complex (including UPF1 bound to release factors at the stalled ribosome) is believed to activate NMD. In cooperation with UPF2 stimulates both ATPase and RNA helicase activities of UPF1. Binds spliced mRNA upstream of exon-exon junctions. In vitro, stimulates translation; the function is independent of association with UPF2 and components of the EJC core.
Synonyms: hUpf3B; RENT3B; UPF3X; MRX82; MRX62; MRXS14; UPF3BP1; UPF3BP2; UPF3BP3; Upf3p-X
Tractability: Small molecule: a structure with a bound ligand is known. PROTAC: ubiquitination databases record sites on it; its protein half-life has been measured.
Gene: Protein-coding gene on chromosome X (119,833,808 to 119,853,083, reverse strand). Ensembl gene ENSG00000125351.
Subcellular location: Nucleus; Cytoplasm
Subcellular location (Human Protein Atlas): Cytosol; Nucleoli; Nucleoplasm
Pathways (Reactome):
Metabolism of RNA: Nonsense Mediated Decay (NMD) enhanced by the Exon Junction Complex (EJC); Transport of Mature mRNA derived from an Intron-Containing Transcript; mRNA 3'-end processing; mRNA Splicing - Major Pathway
Developmental Biology: Regulation of expression of SLITs and ROBOs
Gene Ontology:
Molecular function: mRNA binding; protein binding; RNA binding; nucleic acid binding
Biological process: nuclear-transcribed mRNA catabolic process, nonsense-mediated decay; positive regulation of translation; positive regulation of nuclear-transcribed mRNA catabolic process, nonsense-mediated decay; RNA surveillance
Cellular component: cytosol; exon-exon junction complex; nucleolus; nucleoplasm; nucleus; cytoplasm; nonsense-mediated decay complex; neuronal cell body
Gene-disease validity (ClinGen):
ClinGen rates the evidence that UPF3B causes each of these diseases.
X-linked complex neurodevelopmental disorder (X-linked): Definitive. A complex neurodevelopmental disorder that is transmitted via X-linked inheritance, and is characterized by intellectual disability, autism and epilepsy.
Homologues: Orthologues: chimpanzee UPF3B (100% identical), macaque UPF3B (99% identical), pig UPF3B (95% identical), rabbit UPF3B (95% identical), rat Upf3b (88% identical), mouse Upf3b (85% identical), zebrafish upf3b (55% identical), tropical clawed frog upf3b (54% identical), dog UPF3B (53% identical), Drosophila melanogaster Upf3 (27% identical), Caenorhabditis elegans smg-4 (19% identical). Paralogues in human: UPF3A (44% identical).
Diseases named in the same sentence as UPF3B in open-access papers:
UPF3B is named in the same sentence as 73 diseases in open-access papers, as found by Europe PMC text mining. Sharing a sentence is not in itself a finding about the gene and the disease. The quoted sentences say what the papers report.
Intellectual disability (15 papers, 2013 to 2025). "In humans, nonsense and missense mutations in the lone X-linked UPF3B gene in males cause intellectual disability." (PMID 40366162, 2025). "UPF3B gene mutations are known to cause intellectual disability and are associated with neuropsychiatric disorders, including schizophrenia, autism spectrum disorder, and ADHD." (PMID 40366162, 2025). "In humans, mutations in the NMD gene, UPF3B, cause intellectual disability, and several other NMD genes have been shown to be significantly associated with neurodevelopmental disorders." (PMID 40366162, 2025). "There is considerable interest in UPF3B, particularly since mutations in the UPF3B gene cause intellectual disability and are associated with neurodevelopmental disorders in humans." (PMID 40366162, 2025). "In humans, UPF3B mutations cause intellectual disability and are associated autism and schizophrenia." (PMID 40366162, 2025). "UPF3B mutations cause intellectual disability with impairment of neural stem cell differentiation and reduction in neuronal branching, through a loss of UPF2 interaction leading to NMD abrogation." (PMID 37605642, 2023). "The mutation of UPF3B causes multiple psychiatric illnesses, such as intellectual disability (ID) and schizophrenia (SCZ)." (PMID 36194583, 2022). "UPF3B encodes a protein that participated in nonsense-mediated mRNA decay, and the mutation of UPF3B was associated with mental retardation." (PMID 33251144, 2020). "Pedigree analysis of numerous families harboring mutations in the UPF3B gene have demonstrated that both nonsense and missense mutations cause intellectual disability in humans." (PMID 32773035, 2020). "For example, single allele UFP2 deletions and mutations of UPF3B have been identified in patients with intellectual disability (ID)." (PMID 32718059, 2020). "Germline mutations in the NMD factor gene UPF3B that abrogate normal UPF3B function cause various forms of intellectual disability and other mental disorders." (PMID 32718059, 2020). "UPF3B is encoded by an X-linked gene that when mutated causes intellectual disability and is associated with neurodevelopmental disorders, including schizophrenia and autism." (PMID 29333258, 2017). "NMD efficiency varies in different tissues, loss-of-function mutations in Upf genes in mice alter expression of a subset of transcripts, and loss-of-function mutations in Upf3b in humans are associated with intellectual disability." (PMID 23359859, 2013). "Similarly, heterozygous deletions of UPF2, which directly interacts with UPF3B, cause intellectual disability." (PMID 38791071, 2024). "NMD has also an important role in neuronal development as demonstrated by the fact that mutations, as well as copy number variations in UPF2 and UPF3B, lead to intellectual disability and/or neurodevelopmental disorders in humans, including schizophrenia and autism spectrum disorder." (PMID 37605642, 2023). "It will be intriguing to determine whether humans with UPF3B mutations also suffer from neuro-inflammation and whether this is responsible for their intellectual disability." (PMID 32773035, 2020). "In addition, we discovered a hemizygous mutation (p.Leu295Met) in UPF3B which have been reported as a causative gene of X-linked recessive mental retardation." (PMID 26544041, 2015). "Studies showed that Upf3b-dependent NMD regulates the development of neural cells and that loss-of-function mutation leads to intellectual disability, autism, childhood onset schizophrenia, and attention deficit hyperactivity disorder." (PMID 38791071, 2024). "UPF3A and its paralog UPF3B antagonistically regulate NMD, and both have been implicated in ASDs, intellectual disability, and schizophrenia." (PMID 36618441, 2021). "In fact, changes in mRNA levels of the NMD-members SMG5 and UPF3B have been associated with intellectual syndromic and non-syndromic intellectual disability, autism, childhood onset schizophrenia and ADHD." (PMID 38637827, 2024).
Intellectual disability (continued). "In addition, they may also help to better understand the link between UPF3B and intellectual disability and which domains of UPF3A modulate the severity of the disease and may therefore be potential targets for therapy." (PMID 35451084, 2022).
autism (8 papers, 2015 to 2025). Persistent deficits in social interaction and communication and interaction as well as a markedly restricted repertoire of activity and interest as well as repetitive patterns of behavior. "We have shown that UPF3B proteins with missense mutations found in patients with autism, schizophrenia and XLID are functionally impaired in NMD." (PMID 26012578, 2015). "Mutation in the UPF3B gene on chromosome X is implicated in neurodevelopmental disorders including X-linked intellectual disability, autism and schizophrenia." (PMID 26012578, 2015). "UPF3B- and UPF2-related disorders recapitulate many of the phenotypes observed in patients carrying the UBAP2L variant, including mild to severe ID, autism-like behaviors, and seizures." (PMID 35977029, 2022). "Mutation in the UPF3B gene located on chromosome Xq24 has been implicated in X-linked intellectual disability (XLID), autism and schizophrenia." (PMID 26012578, 2015). "Human UPF3B, encoded by the X-linked gene UPF3B, was the first NMD factor linked with human neurodevelopmental syndromes such as X-linked intellectual disability (ID) with and without autism, childhood onset schizophrenia (COS) and attention deficit hyperactivity disorder (ADHD)." (PMID 34943873, 2021). "This is the first report of a premature termination codon before the three functional domains of the UPF3B protein and these results directly implicate the absence of these domains with XLID, autism and some dysmorphic features." (PMID 31737052, 2019).
schizophrenia (7 papers, 2015 to 2025). A major psychotic disorder characterized by abnormalities in the perception or expression of reality. "UPF3B missense mutations are found in patients with schizophrenia and X-linked intellectual disability (XLID)." (PMID 39138189, 2024). "Deletion of the UPF3B gene is associated with childhood onset schizophrenia.Throughout development UPF3B expression and localization vary." (PMID 35406756, 2022). "In addition, UPF3B mutations in humans are associated with schizophrenia, autism spectrum disorder, and attention deficit-hyperactivity disorder (ADHD)." (PMID 40366162, 2025). "In addition, mutation in UPF3B is described in schizophrenia." (PMID 26012578, 2015). "Mutations in crucial NMD components, such as UPF3B, have been identified in a diversity of neurological diseases ranging from ASD to schizophrenia." (PMID 35406756, 2022).
colorectal cancer (3 papers, 2022 to 2024). A primary or metastatic malignant neoplasm that affects the colon or rectum. "To study UPF3B‐independent NMD, we used CRISPR‐Cas9‐based gene editing to generate two independent UPF3B loss of function alleles in human colorectal carcinoma HCT116 cells, a near diploid cell line with only one copy of UPF3B." (PMID 35451102, 2022). "We show that in human colorectal cancer HCT116 cells, NMD can operate in a UPF3B‐dependent and ‐independent manner." (PMID 35451102, 2022).
esophageal cancer (3 papers, 2020 to 2024). A primary or metastatic malignant neoplasm involving the esophagus. "Studies also suggest the UPF3B can be used as factors of gene models to predict tumor progression in various types of tumors, including esophageal cancer, liver cancer." (PMID 36194583, 2022). "A significant correlation was found between the expression of UPF3B and the pathological stage of Esophageal Carcinoma (ESCA), Kidney Chromophobe (KIHC), Liver Hepatocellular Carcinoma (LIHC), and Skin Cutaneous Melanoma (SKCM)." (PMID 36194583, 2022). "For instance, UPF3B is upregulated in esophageal carcinoma, stomach adenocarcinoma, hepatocellular carcinoma, and breast invasive carcinoma, whereas UPF3B was downregulated in kidney chromophobe, prostate adenocarcinoma, and thyroid carcinoma." (PMID 33193701, 2020).
hemophilia (3 papers, 2018 to 2022). Hemophilia is a genetic disorder characterized by spontaneous hemorrhage or prolonged bleeding due to factor VIII or IX deficiency. "We previously demonstrated that inhibition of NMD by ASO-mediated reduction of a branch-specific NMD factor, Upf3b, significantly stabilized hFIX mRNA harboring an early nonsense mutation (R29X) and significantly improved the efficacy of read-through therapy in this mouse hemophilia model." (PMID 31070517, 2019). "For example, we have previously shown ASO-mediated depletion of branch-specific NMD factor UPF3B was well tolerated in mice with minimal impact on the normal transcriptome while alleviating disease phenotypes in a hemophilia mouse model." (PMID 35487895, 2022). "Overall, our results suggested that the UPF3B-dependent NMD pathway plays an important role in degrading PTC-containing mutant transcripts in both mdx and hemophilia mouse models, which seems to be in accordance with a recent report that assigned a central role for UPF3B in the NMD pathway." (PMID 29334995, 2018). "Furthermore, when combined with reagents promoting translational read-through, Upf3b-ASO treatment leads to the production of functional factor IX protein in hemophilia mice." (PMID 29334995, 2018). "Further, we demonstrated that Upf3b-ASO treatment significantly enhanced the efficacy of read-through therapy and led to improved coagulation activity in a hemophilia mouse model." (PMID 29334995, 2018). "While minimally impacting the normal transcriptome, Upf3b-ASO treatment significantly stabilizes the PTC-containing dystrophin mRNA in mdx mice and coagulation factor IX mRNA in a hemophilia mouse model." (PMID 29334995, 2018). "Although it significantly increased the PTC-containing transcript levels, Upf3b-ASO treatment alone did not ameliorate disease phenotypes in either mdx or hemophilia mouse model." (PMID 29334995, 2018). "The amount of hFIX protein detected in male hemophilia mice with either the combination of Upf3b-GalNAc-ASO and Gspt1-GalNAc-ASO, or the combination of Upf3b-GalNAc-ASO and geneticin, although reliably detected, remained lower than the threshold 1% of hFIX-WT abundance." (PMID 29334995, 2018).
hepatocellular carcinoma (3 papers, 2020 to 2024). A malignant tumor that arises from hepatocytes. "For instance, UPF3B and SMG5 are highly expressed in hepatocellular carcinoma (HCC) tissue and are associated with poor prognosis in these patients." (PMID 36979701, 2023).
liver cancer (3 papers, 2021 to 2024). An epithelial or non-epithelial malignant neoplasm that arises from the liver. "UPF3B encodes a protein that is part of a post-splicing multiprotein complex involved in both mRNA nuclear export and mRNA surveillance, and it has been reported to have an effect on the prognosis of patients with liver cancer." (PMID 33516217, 2021). "The proteins level of UPF3B was significantly increased in different types of cancers, including Colon cancer, Ovarian cancer, lung cancer, Liver Cancer." (PMID 36194583, 2022). "In summary, we first investigated the expression of UPF3B in pan cancer-TCGA and the liver cancer tissues collected from our own hospital to validate our analysis, the results showed that it differentially expressed between tumor and normal tissues." (PMID 36194583, 2022). "We also found the mitosis, G1/S transition and so on that involved in cell cycle processes were greatly affected in liver cancer patients with high UPF3B." (PMID 36194583, 2022). "The protein levels of UPF3B also corresponded to mRNA expression in colon cancer, lung cancer and liver cancer but in opposite direction in pancreatic cancer and glioblastoma." (PMID 36194583, 2022). "Moreover, we performed a qRT-PCR to validate the expression of UPF3B using 13 paired samples from liver cancer patients." (PMID 36194583, 2022). "Moreover, among of them, RFC4, ZWINT, UPF3B, NCBP2, ADA, SF3A3 and GTF2H1 are independent prognostic indicators of liver cancer." (PMID 33516217, 2021).
prostate adenocarcinoma (3 papers, 2020 to 2024). "Conversely, UPF3B is expressed at a low level in Kidney Chromophobe (KICH), Prostate Adenocarcinoma (PRAD), Thyroid Carcinoma (THCA)." (PMID 36194583, 2022).
mental disorder (2 papers, 2015 to 2020). A disease that has its basis in the disruption of mental process. "Moreover, loss of function UPF3B mutations in humans not only cause deficiencies in NMD but also lead to a variety of mental disorders that highlight the importance of UPF3B for human health." (PMID 25429978, 2015).
Pancreatic Cancer (2 papers, 2022 to 2024). "In contrast, UPF3B protein expression was markedly decreased in UCEC, pancreatic cancer, and glioblastoma." (PMID 36194583, 2022).
developmental and epileptic encephalopathy 94 (1 paper, 2024). Developmental and epileptic encephalopathy-94 (DEE94) is a severe form of epilepsy characterized by onset of multiple seizure types in the first few years of life and associated with poor prognosis. "Defects in Chromodomain Helicase DNA-Binding Protein 2 (CHD2) are known to cause developmental and epileptic encephalopathy 94 (MIM#615369), whereas Regulator of Nonsense-Mediated mRNA Decay (UPF3B) is associated with X-linked syndromic intellectual developmental disorder 14 (MIM#300676)." (PMID 37563452, 2024).
Duchenne muscular dystrophy (1 paper, 2018). Duchenne muscular dystrophy (DMD) is a neuromuscular disease characterized by rapidly progressive muscle weakness and wasting due to degeneration of skeletal, smooth and cardiac muscle. "Since the Upf3b-ASO effectively depleted cells of Upf3b and was well tolerated in normal animals, we tested the Upf3b-ASO in mdx mice, a model of Duchenne muscular dystrophy (DMD)." (PMID 29334995, 2018).
female infertility (1 paper, 2022). Diminished or absent ability of a female to achieve conception. "Similarly, UPF3B, IRF8, and PSMB1 were the top 3 hub genes identified with the female infertility network." (PMID 35918717, 2022).
osteosarcoma (1 paper, 2024). A usually aggressive malignant bone-forming mesenchymal neoplasm, predominantly affecting adolescents and young adults. "First, the endogenous interaction between IRE1α and UPF3B was confirmed by co-immunoprecipitation assays in both HEK293T cells and the human osteosarcoma cell line, U2OS cells." (PMID 39138189, 2024).
testicular germ cell tumor (1 paper, 2022). A germ cell tumor arising from the testis. "Additionally, UPF3B expression was positively correlated with most immunoinhibitors, including TGFBR1, IL10RB, CD160, CD274, TIGIT and PDCD1 in UVM, OV, KIHC, and LIHC, but negatively associated with the expression of majority genes in STAD and Testicular Germ Cell Tumors (TGCT)." (PMID 36194583, 2022).